EGFR (epidermal growth factor receptor)
Diseases named in the same sentence as EGFR in open-access papers (continued):
Sharing a sentence is not in itself a finding about the gene and the disease.
tumor (continued). "Mutations or overexpression of EGFR genes leads to tumor progression and drug resistance in various cancer types including breast." (PMID 29455658, 2018). "In conclusion, the current study shows that trastuzumab-paclitaxel induces objective tumour responses in an important number of patients with EGFR mutation positive NSCLC that show HER2 expression after progression on an EGFR TKI." (PMID 30061586, 2018). "Recent advances made it possible to identify some mutations (e.g., EGFR mutations) in circulating tumor DNA, obtained from peripheral blood." (PMID 30110953, 2018). "In selected patients, a microdissection analysis of the adenomatous and squamous components present in each tumor was performed, showing that both exhibit the same EGFR or KRAS mutations." (PMID 30060526, 2018). "In order to gather more information on the relevance of the individual tumor biology, additional translational studies should be included in the approaching trials, assessing the actual correlation between EGFR mutations and efficacy of the vaccine." (PMID 29661145, 2018). "As expected, the EGFR sensitizing mutation identified originally in the tumor sample was also detected in all the baseline plasma samples (treatment naïve patients)." (PMID 29416630, 2018). "We define in EOCs E-cadherin as a tumor enhancer that positively contributes to EGFR-promoting growth signaling due to loss of PLEKHA7 expression." (PMID 29996940, 2018). "The surviving tumour cells were profiled for their expression of Snail and epidermal growth factor receptor (EGFR), which has been linked with tumour metastasis and treatment resistance." (PMID 29311580, 2018). "For the ADC-only group, the univariate logistic regression analysis showed that sex, smoking status, pSUVmax, tumor size, nodal involvement and tumor stage were associated with EGFR mutations." (PMID 29164298, 2018). "Establishing the tumor-associated ST6Gal-I sialyltransferase as a regulator of EGFR provides novel insight into the role of glycosylation in growth factor signaling and chemoresistance." (PMID 29402301, 2018). "Samples from the 376 patients with tumor cells found on their brushing smears underwent RT-PCR and Sanger sequencing for EGFR mutation analysis." (PMID 29643378, 2018). "It has been shown that ALK-positive patients have higher levels of vascular endothelial growth factor-A (VEGF-A) and tumor vessel formations compared to EGFR and KRAS mutated NSCLC." (PMID 29318404, 2018). "The most common application to date has been the imaging of overexpressed antigen‐associated tumours; the human epidermal growth factor receptor (HER1, HER2 and HER3) being the most widely investigated." (PMID 30246488, 2018). "Since the first discovery of its oncogenic kinase domain mutations, EGFR has been considered a key oncodriver for many tumor types, including non-small cell lung cancer (NSCLC) and colorectal cancer (CRC)." (PMID 29642553, 2018). "EGFR expression at >50% of tumour cells with positive EGFR immunostaining was associated with poorer overall survival (p = 0.020)." (PMID 29731973, 2018). "Proliferation of (tumour) cells, one of the effects associated with the EGFR signalling pathway, can be visualised and evaluated with positron emission tomography (PET) using 3′-deoxy-3′-[18F]fluorothymidine ([18F]FLT)." (PMID 29594931, 2018). "This suggests an association between rapid tumor apoptosis as well as the EGFR-TKI's target (EGFR) and the development of LCV." (PMID 29732013, 2018). "We were able to detect the T790M mutation by analysis of plasma cell-free tumor DNA with the cobas EGFR Mutation Test (Roche), however, allowing a switch to osimertinib only 5 days after disease progression during gefitinib treatment." (PMID 30034636, 2018). "Trastuzumab-paclitaxel induces objective tumour responses in 46% of EGFR TKI pretreated patients with an activating EGFR mutation and HER2 expression." (PMID 30061586, 2018).
tumor (continued). "HER2 expression and amplification are observed in ~15% of tumour biopsies from patients with a sensitising EGFR mutation who develop EGFR TKI resistance." (PMID 30061586, 2018). "Remarkably, inhibition of FASN by Orlistat in EGFR mutated NSCLC suppresses tumor growth in vitro and in vivo through reducing EGFR palmitoylation but inducing mutant EGFR ubiquitination and subsequent proteasomal degradation." (PMID 29907133, 2018). "It is clear that tumor heterogeneity and clonal selection of pre-existing resistant cells with EGFR T790M mutations is one mechanism for the development of resistance." (PMID 30097569, 2018). "Among the 24 EGFR mutated tumor samples, both methods detected EGFR exon 19 delins in 14 samples (58%)." (PMID 30647840, 2018). "The results revealed that loss of HCRP-1 promoted tumor metastasis in vivo and activated the EGFR and AKT signaling pathway, which was consistent with the results obtained in in vitro experiments." (PMID 30518879, 2018). "Four patients had an activating mutation in EGFR (L858R or exon 19 deletions) in both the primary tumor and their corresponding BM." (PMID 30186753, 2018). "Elevated tumor EGFR expression level is linked to tumor aggressiveness and radioresistance constituting a major challenge for successful therapy of locally advanced HNSCC." (PMID 30042828, 2018). "The substitution of threonine with methionine at amino acid position 790 (T790M), as the second mutation in EGFR, is the most common resistance mechanism and is detected in tumor cells from more than 50–60% of patients after disease progression." (PMID 29713646, 2018). "Further, reduced tumor size was paralleled by lower FFAs levels, as well as loss of EGFR, FASN, and survivin expression, concomitant to upregulation of Bax and Bak proteins in in situ tumors." (PMID 29449326, 2018). "The concordance rate between the EGFR mutation status in the tumor and plasma samples was 88.8% (95% CI 82.5–93.5)." (PMID 29623586, 2018). "EGFR mutation analysis was performed on biopsy tumour samples in 123 (68.7%) patients and on cytology specimens in 55 (30.7%) patients." (PMID 29382302, 2018). "Epidermal Growth Factor Receptor (EGFR) circulating cell-free tumor DNA (ctDNA) mutational analysis was performed using digital droplet PCR (ddPCR)." (PMID 30150518, 2018). "The high concordance between the different DNA sources for EGFR mutation testing supports the use of plasma samples when tumor tissue is unavailable." (PMID 29623586, 2018). "Overall, it is feasible to detect tumor-derived T790M mutations in the EGFR gene using cfDNA from patients with NSCLC using Super ARMS." (PMID 30337598, 2018). "This differs from HPV-negative OPC, which is associated with tobacco and alcohol use, poor oral hygiene, and usually has a large number of deletions or mutations on the tumor suppressor genes and a higher tumor EGFR expression." (PMID 30304096, 2018). "In recent years, there are some inconsistent views concerning the influence of ErbB2 dysregulation on the susceptibility of tumor cells to EGFR-TKIs in NSCLC." (PMID 29455669, 2018). "To investigate the mechanism involved in this and also the possible effects of p110α RBD mutation on oncogenic EGFR-induced tumor formation, we tested the effect of endogenous expression of RBD-mutant p110α on EGFR signaling." (PMID 30590030, 2018). "The most commonly used EGFR mutation testing method for the tumor tissue samples was the QIAGEN Therascreen® EGFR RGQ PCR kit (52.1%)." (PMID 29623586, 2018). "We successfully detected EGFR mutations in UcfDNA which also found in the corresponding tumor tissue samples, demonstrating the UcfDNA extraction and genotyping was possible from urine samples of cancer patients." (PMID 30400835, 2018). "Overexpression of the epidermal growth factor receptor (EGFR) in metastatic ccRCC is associated with high tumor grade." (PMID 30046388, 2018).
tumor (continued). "Although both tumor types depend on the mutation for growth, clinical benefit of EGFR tyrosine kinase inhibitors (TKIs) has only been observed in LUAD patients and, thus-far, not in GBM patients." (PMID 30518123, 2018). "Several previous studies have reported the feasibility of detecting resistance and sensitizing EGFR mutations in plasma samples and the early prediction of tumor progression compared to CT-scans using liquid biopsy." (PMID 29416630, 2018). "The results were correlated with tumor characteristics including EGFR expression, KRAS mutation, and CRT response based on the pathologic tumor regression grade (TRG)." (PMID 30186857, 2018). "In a cohort of 154 eligible patients, EGFR mutations were identified in 15.1 and 11.0% of tumor and plasma samples, respectively." (PMID 29623586, 2018). "As a correlative study, MET copy number analysis and the presence of the EGFR mutation were determined in these 58 tumor samples." (PMID 29416799, 2018). "We have reported that TAMs in tumor tissue was correlated to treatment failure of first line EGFR-TKI in an EGFR mutation unselected cohort." (PMID 29484139, 2018). "A single arm phase II study was performed to study the safety and efficacy of trastuzumab and paclitaxel treatment in patients with a sensitising EGFR mutation who show HER2 expression in a tumour biopsy (IHC ≥ 1) after progression on EGFR TKI treatment." (PMID 30061586, 2018). "We here characterized differential effects of the two KAI1 variants on tumor biological events involving integrin (αvß3) and/or epidermal growth factor receptor (EGF-R)." (PMID 29464079, 2018). "Repeat tumor biopsy to detect the EGFR T790M mutation is the current standard of care, and osimertinib has been approved for patients with acquired EGFR T790M-mutant disease." (PMID 29455650, 2018). "First, we found a strong concordance between EGFR status in tumour and plasma samples, and showed that mutations in multiple cancer‐related genes can be identified directly in plasma by targeted sequencing." (PMID 29848757, 2018). "Tumor cells harboring HER2 mutations have been associated with response to EGFR-TKIs that target both EGFR and HER2 (e.g., afatinib, lapatinib) but not to those that target EGFR alone." (PMID 30356721, 2018). "Elevated EGFR activation is known to promote survival, proliferation, and invasion of tumor cells under hypoxia, and multiple mechanisms have been linked to hypoxia-induced EGFR activation." (PMID 30285805, 2018). "All the studies analyzed both sensitivity and specificity of ctDNA analysis for the detection of EGFR-T790M mutation as compared to the gold standard tumor tissue." (PMID 30190486, 2018). "The T2 tumor carries the L858R/T790M mutation and the patient progressed on dacomitinib, a second-generation EGFR inhibitor." (PMID 29651165, 2018). "Since Reactome “YAP1 and TAZ stimulated gene expression” gains cePathway relationships with several tumor-associated growth factor pathways (e.g. EGFR, TGFβ and IGF), YAP and TAZ would promote the growth factor pathways possibly through ceRNA relationships." (PMID 29565967, 2018). "Two patients displayed different mutations with respect to the primary tumor, and in two out of the four patients with a wild type primary tumor, new mutations were highlighted: EGFR p.746_750del and KRAS p.G12V." (PMID 30110953, 2018). "Results from the prediction model suggest that tumor heterogeneity is associated with EGFR mutation." (PMID 30559455, 2018). "Sidedness of the primary tumour is a surrogate prognostic biomarker, and lesions originating from right-sided primary tumours harbour genetic alterations associated with resistance to anti-EGFR therapy." (PMID 30094460, 2018). "At disease progression, a biopsy of tumor tissue is typically performed to evaluate for targetable resistance mechanisms such as EGFR T790 M mutation." (PMID 29455654, 2018).
tumor (continued). "Mutations that show response to EGFR-TKIs in LUAD have sporadically been identified in other tumor types." (PMID 30518123, 2018). "Currently, the parallel detection of (known) primary activating EGFR mutations and/or other tumor-specific mutations are helpful to ensure the presence of tumor-derived cfDNA in diagnostic LB samples." (PMID 29719623, 2018). "The present post hoc analysis of the Spanish subset of patients in the ASSESS study further confirms the utility of ctDNA analysis in plasma for the evaluation of EGFR mutation status when tumor tissue is unavailable or exhausted." (PMID 29623586, 2018). "Second, there are many significant differences with regard to clinical characteristics between the EGFR mutations and EGFR wild-type groups, including case number, age, stage distribution and tumor size." (PMID 29447182, 2018). "A large meta-analysis reviewing 25 studies (2,605 NSCLCs) found a high concordance rate in EGFR mutation profiles between blood and tumor tissue." (PMID 29441349, 2018). "Tumor-specific cfDNA levels were confirmed using digital PCR analysis with matched plasma cfDNA from patients positively diagnosed with EGFR mutation and who provided sufficient DNA for sequence analysis." (PMID 29721209, 2018). "The total rate of EGFR mutation was 56% (60/107) in all plasma samples and 77.6% (83/107) in corresponding tumor tissues." (PMID 29764589, 2018). "The presence of KRAS mutations in this tumor indicates that EGFR-targeted therapy is likely to be ineffective." (PMID 29879069, 2018). "MGH121 was originally derived from a biopsy of a resistant EGFR-mutant tumor with an EGFR-activating mutation (del19) and which had developed a T790M secondary mutation in the clinical tumor after 7 months’ administration of erlotinib." (PMID 29416720, 2018). "In fact, IGF-1R expression is correlated with higher tumor grade, and its co-expression with epidermal growth factor receptor (EGFR) was shown to be be significantly associated with poor survival in PDAC." (PMID 29475434, 2018). "In 43 patients with known EGFR mutations from tumour, we identified them accurately in plasma of 41 patients (95%, 41/43)." (PMID 29848757, 2018). "The correlation between serum tumor biomarker levels and chemotherapy responses and their association with epidermal growth factor receptor (EGFR) mutation status and progression‐free survival (PFS) were analyzed." (PMID 29767438, 2018). "The most frequent mutations in this gene are associated with poor survival, increased tumor aggressiveness and resistance to therapy with anti-epidermal growth factor receptor (EGFR) antibodies." (PMID 29304017, 2018). "We show that the differences (i.e., the diverse mutation rates of EGFR) are mainly attributed to a subtype of patients with enriched inflammatory tumor-infiltrating lymphocytes (TILs)." (PMID 29799009, 2018). "Wei B implicated that tumor genesis driven by different EGFR mutations were mechanistically different." (PMID 30383772, 2018). "Patients with epidermal growth factor receptor (EGFR) variant III-negative/YKL-40-negative tumors have a better prognosis than other tumor subtypes." (PMID 29467925, 2018). "In a phase I clinical trial, the PI3K inhibitor temporarily decreased the size of the tumor in a patient with EGFR L858R/T790M/PIK3CA mutation after progression during treatment with erlotinib." (PMID 30445769, 2018). "For the NSCLC patients that subsequently developed brain metastasis, 75% (9 of 12) of the primary tumor samples contained an EGFR variant while the brain metastases had variants in 87% (7 of 8)." (PMID 29899834, 2018). "With respect to PFS, univariate analysis showed that male gender, PS ≥ 2, tumor stage IV and wild-type EGFR status were significantly associated with worse PFS." (PMID 27863417, 2017). "In this subgroup, EGFR protein overexpression was significantly associated with poor differentiation of the tumor cells and lymph node metastasis, especially extra-capsular spread." (PMID 28694429, 2017).
tumor (continued). "Expression profiling of miRNAs associated with EGFR mutational status in tumor tissues and bloodstream have been extensively investigated to translate specific miRNAs as prediction biomarker." (PMID 29383112, 2017). "Tumor cells bearing these mutations become highly dependent of the EGFR signal and thus are highly sensitive to EGFR tyrosine kinase inhibitors (EGFR-TKIs)." (PMID 28671975, 2017). "The addiction of these tumors to EGFR signaling is further demonstrated by the emergence of the secondary activating T790M mutation as a major cause of tumor resistance to gefitinib." (PMID 28435746, 2017). "EGFR mutation analysis is necessary for drug prescription purpose and therefore tumor tissue is always required." (PMID 28107191, 2017). "Of the 16 FFPE samples in which an EGFR L858R mutation was identified in the tumor, 16 were positive for the same mutation as that assessed in the multiplex ddPCR assay." (PMID 28625519, 2017). "Overall, preclinical experiments have demonstrated that VEGF signaling plays an important role in anti-EGFR therapy resistance and the combination of VEGFR and EGFR inhibitors has been associated with improved anti-tumor activity in xenografts." (PMID 28002810, 2017). "Dysregulation of EGFR pathways by overexpression or constitutive activation can enhance certain aspects of tumor progression, including metastasis, and is associated with poor prognosis in various human malignancies." (PMID 29100426, 2017). "KRAS gene copy number loss in tumor DNA is associated with better treatment response to anti‐EGFR drugs even in the presence of KRAS mutation in the tumor." (PMID 28504856, 2017). "We further demonstrated that this pathology-determined OS can be affected by both tumor stage and status of oncogenic mutations in EGFR, KRAS, ALK, RET, and BRAF genes." (PMID 29137260, 2017). "EGFR is shown mutated in a number of tumor types, such mutation leads to its constant activation, which produces uncontrolled cell proliferation." (PMID 29018350, 2017). "In these cases, the originally detected activating EGFR mutation (e.g. p.L858R) was always present, while the p.T790M alterations always showed lower VAFs in each case suggesting tumor heterogeneity (5.4-12.2% VAF versus 8.1-88% VAF for activating mutations)." (PMID 28415793, 2017). "For the 116 patients with plasma samples analyzed by ARMS-Plus, 44 (37.9%) of them were harboring EGFR activating mutations in tumor tissue." (PMID 29340107, 2017). "In NSCLC, several studies have reported that acquisition of EMT is associated with EGFR TKI resistance in EGFR-mutant cell lines and tumor specimens." (PMID 29190911, 2017). "Better knowledge of tumor biology, especially of specific molecular alterations such as mutations of the epidermal growth factor receptor (EGFR) and the KRAS gene led to the discovery of the biomarkers used as target therapies." (PMID 29285236, 2017). "In fact, preclinical data supported that EGFR is also expressed in the endothelial cells of tumor vessels and associated with tumor-induced VEGF expression and neovasculature." (PMID 28881856, 2017). "Apply peripheral blood as a surrogate for detecting epidermal growth factor receptor mutation status in tumor, also called liquid biopsy, has been reported to be a feasible method in patients with advanced non-small lung cancer." (PMID 29100447, 2017). "In the matched plasma samples, the EGFR mutations positive rate was 45.9% (50/109), which is similar to what in tumor tissue (P = 0.1359)." (PMID 28829813, 2017). "Initially, patients with tumours that had mutations of exon 2 of the KRAS oncogene were found to be resistant to treatment with anti-EGFR mAbs." (PMID 29183279, 2017). "EGFR overexpression results in increased tumor cell motility in vivo and is associated with enhanced intravasation and metastasis." (PMID 29237412, 2017).